EGF (epidermal growth factor)
Diseases named in the same sentence as EGF in open-access papers (continued):
Sharing a sentence is not in itself a finding about the gene and the disease.
tumor (continued). "EMT in cancer is induced by signals from the tumor-associated stroma, including epidermal growth factor (EGF), platelet-derived growth factor (PDGF), hepatocyte-derived growth factor (HGF), and transforming growth factor beta (TGF-β)." (PMID 29922644, 2018). "The signaling pathway induced by EGF or insulin are also associated with tumor cell proliferation and migration." (PMID 29020972, 2017). "Tumor-associated macrophages can secret EGF to the microenvironment that promotes tumor growth, can play an important role in the regulation of YAP1 expression." (PMID 29163769, 2017). "In the present study, we investigated the role of EGF in the metabolism of 5-ALA as a possible cause of variability in tumor-associated fluorescence in GBM cells." (PMID 28500562, 2017). "Next, we compared the proliferative activity of leptin in 1321N1 cells with known mitogens implicated in tumor pathogenesis such as EGF or sPLA2-IIA." (PMID 28249041, 2017). "The increase in phosphorylated EGFR in FLCN−/− and tumour-associated mutants was most pronounced at 1 h after EGF treatment, but remained high at the 3 h time point." (PMID 28656962, 2017). "FGF2, HGF and EGF are associated with the angiogenesis, growth, proliferation and differentiation of numerous cell types, including certain tumor cells." (PMID 28486560, 2017). "The treatment of co-cultured SHH MB cell spheroids with EGF for five days caused massive and well quantifiable dissemination of the tumour cells." (PMID 28706234, 2017). "Ligand targeting of nanoparticles is a common targeting strategy, with tumor-associated dysregulated expression of the receptors of transferrin, folic acid, epidermal growth factor, and hyaluronic acid being particularly popular." (PMID 28325291, 2017). "The monotherapy with HisDianthin‐EGF also caused a decrease in tumor volume (40.8 ± 61.3 mm3), which was a 51.7% average reduction when compared to placebo; however, treatment together with SO1861 resulted in a more than 13‐fold better efficacy." (PMID 28755527, 2017). "Tumor development was associated with the appearance of F4/80+CD11bhighGr1low M2 macrophages that produced the tumor-promoting factors IL-6 and EGF, in a CD1d- and IL-13-dependent manner." (PMID 29375569, 2017). "These tumor-associated leukocytes drive tumor growth by releasing growth factors, such as epidermal growth factor (EGF), vascular endothelial growth factor (VEGF) and fibroblast growth factor 2 (FGF2)." (PMID 27589805, 2016). "The rs4444903 polymorphism (A61G) within the EGF gene promoter region is associated with EGF levels and various neoplastic diseases." (PMID 26930482, 2016). "Overall, these data suggest that PBX1 underlies the expression of EGF dependent genes involved in aggressive tumour progression." (PMID 26215677, 2015). "Numerous angiogenic factors including vascular endothelial growth factor (VEGF), epidermal growth factor (EGF), basic fibroblast growth factor (bFGF) and angiopoietin have been implicated in tumor angiogenesis." (PMID 25415226, 2015). "These processes include proteins involved in cell adhesion, bony reconstruction, tumor front, apoptosis regulation, cell cycle/cell proliferation, and epidermal growth factor gene and BRAF V600 E mutations." (PMID 26823641, 2015). "EGF and its receptor have been classically linked to an over-expression in several tumor cell lines and related to poor prognosis and decreased survival." (PMID 24495355, 2014). "Tumor-associated macrophages secrete EGF to neighboring cancer cells, which in turn stimulate macrophages to facilitate intravasation and metastatic dissemination of the cancer cells." (PMID 25566498, 2014). "Earlier transcriptional profiling studies have shown that cyclin D1 is a critical downstream effector of EGFR signaling and EGF-stimulated cyclin D1 expression is closely associated with tumor development caused by enhanced cell survival and proliferation." (PMID 24340049, 2013).
tumor (continued). "Numerous angiogenic factors including vascular endothelial growth factor (VEGF), basic fibroblast growth factor (bFGF), epidermal growth factor (EGF) and angiopoietin have been implicated in tumor angiogenesis." (PMID 24312323, 2013). "Aberrant epidermal growth factor (EGF) signaling is associated with tumor growth in squamous cell carcinoma of the head and neck in humans (HNSCC), and is a major focus of targeted therapy." (PMID 23405260, 2013). "These two proteases cause the release of membrane bound epidermal growth factor (EGF)-like growth factors from tumor cells, suppressing the expression of OPG in osteoblasts and increasing osteoclast differentiation." (PMID 23696795, 2013). "In other words, high levels of EGF or the activation of EGF/EGFR pathway had been found to significantly associate with tumor initiation and proliferation." (PMID 23825635, 2013). "In support of this, Lrig1 regulates EGFR levels in primary human keratinocytes, and loss of Lrig1 results in increased EGF signaling and excess intestinal stem cell proliferation, tumor formation and psoriasis-like hyperplasia in mice." (PMID 24086156, 2013). "Tumor-associated macrophages secrete epidermal growth factor (EGF) and carcinoma cells secrete CSF-1 to set up a paracrine chemotactic loop that induces comigration of both cell types and promotion of invasion and metastasis." (PMID 22505929, 2012). "In different tumor cells, expression of some EGF family members such as EGF or TGF-α is associated with poor patient prognosis or resistance to chemotherapeutics." (PMID 22046506, 2012). "It is noteworthy that EGF produced by tumor-associated macrophages also acts as a chemoattractant in promoting motility of various types of human cancer cells." (PMID 22701712, 2012). "We observed that EGF induced nuclear localization of the MUC1 cytoplasmic domain leading to expression of genes linked to tumor cell invasion and metastasis including TWIST1, SNAI1 and SNAI2." (PMID 22586492, 2012). "More carcinoma-associated EGF-SEA molecules resulted in more captured T cells neighboring to or anchored on the surface of S180 tumor cells." (PMID 21311755, 2011). "To further examine the molecular causes of EGF-induced malignant transformation, we searched promoters of upregulated tumor genes for pair wise combinations of TF binding sites." (PMID 21464922, 2011). "For instance, tumor-associated macrophages establish an EGF-CSF-1 paracrine signaling loop with the tumor cells that promote tumor cell movement." (PMID 21359145, 2011). "After elaborating on downstream effects of EGF-induced tumor development, we reconstructed causes of observed expression changes." (PMID 21464922, 2011). "The concomitant presence of EGFR and its ligand, EGF, is associated with enhanced tumor aggressiveness and shorter survival time." (PMID 22087246, 2011). "For this, we focused our attention, first of all, on genes specifically upregulated in tumor compared to transgenic state, that encode components of the revealed EGF and IGF-2 pathways." (PMID 21464922, 2011). "Non-small-cell lung cancer (NSCLC) is an aggressive disease in which vascular endothelial growth factor (VEGF) and epidermal growth factor (EGF) are implicated in tumour growth, tumour resistance to radiation and chemotherapy, and disease relapse." (PMID 20628392, 2010). "A subpopulation of TAMs, which are associated with factors such as EGF, is able to promote metastasis by guiding tumor cells in the stroma toward blood vessels, where they then escape into the circulation." (PMID 21437225, 2010). "Lu and colleagues demonstrated that EGF treatment of human tumor cells that over express EGFR caused a dramatic alteration in cell-cell contacts and internalization of E-cadherin." (PMID 20540763, 2010). "It was found that polymorphisms in EGF, the gene that encodes EGF, were associated with tumor response in patients who received cetuximab, bevacizumab, and irinotecan." (PMID 20016807, 2009).
tumor (continued). "It is driven by growth factors and inflammatory cytokines, that can be secreted by different stroma cells in the microenvironment, including tumor-associated macrophages (TAMs) such as tumor transforming growth factor β (TGFβ), epidermal growth factor (EGF), and tumor necrosis factor α (TNFα)." (PMID 41462963, 2025). "CCL18 and EGF are implicated in tumor biology; however, their roles in BRCA remain partly defined." (PMID 40692603, 2025). "LAD-1 has been associated with activation of the EGF-to-ERK pathway in tumor cells." (PMID 40789452, 2025). "These visualizations confirm the strength and consistency of the observed associations and support the hypothesis that both CCL18 and EGF integrate into broader transcriptional programs relevant to tumor behavior." (PMID 40692603, 2025). "Paracrine signalling between the M2 macrophages and the tumour cells (mediated by the diffusible species EGF), causes the tumour cells to move with the M2 macrophages, towards the blood vessels, where they intravasate and then metastasise to other parts of the body." (PMID 40762719, 2025). "Furthermore, USP11 deficiency suppressed tumor spheroid formation in response to EGF, HKLM (a TLR2 agonist), and LPS (a TLR4 agonist), whereas USP11 overexpression amplified these effects." (PMID 41419456, 2025). "Further comparison of differential signaling flows between the two groups revealed a significant upregulation of signaling pathways associated with tumor metastasis, immune evasion, and inflammatory response, including TGFβ, EGF, and IL2, in the high mRNAsi group." (PMID 40963856, 2025). "In particular, EGF is secreted by tumor-associated macrophages and microglia." (PMID 38393158, 2024). "Tumor-associated macrophages secrete EGF and promote angiogenesis." (PMID 38731434, 2024). "The mechanisms underlying the anti-tumor efforts of EGCG may include the inhibition of epidermal growth factor and IGF/IGF1R signaling pathways as shown in animal and human studies." (PMID 39203871, 2024). "Meanwhile, Zeng and colleagues found that M2-like tumor-associated macrophages-secreted EGF could facilitate epithelial OC metastasis by activating EGFR-ERK signaling and suppressing lncRNA LIMT expression." (PMID 36276992, 2022). "The tumor microenvironment and associated signaling in vivo are likely to be much more complex than that which we can discern using these cell culture experiments, including signaling events in response to defined ligands such as EGF." (PMID 36230550, 2022). "As long‐term culture of GBM cells in either serum or stem cell media with EGF may lead to the loss of tumor OPCs, we reestablished primary GBM cell lines de novo or directly used those freshly isolated from surgical samples to study tumor OPCs from patients." (PMID 33173731, 2020). "Here, in this paper, our results confirmed that WNT7A expression was markedly increased in poorly differentiated tumor tissues compared with matched well-differentiated tumor tissues and that EGF could cause an increase of WNT7A expression in OSCC cells." (PMID 32174831, 2020). "We found that depletion of SHCBP1 remarkably repressed the cellular stemness enhancement caused by EGF stimulation, as revealed by reduced EGF-promoted formation of tumor spheres, expression of stem cell markers, and CD44/EpCAM double-positive as well as SP fraction." (PMID 30177836, 2019). "Finally, both Mo-MDSCs and PMN-MDSCs differentiate into tumor-associated macrophages (TAMs), which facilitate tumor cell growth and survival via secreting IL-6, EGF, and TNF and promote angiogenesis by VEGFA, Semaphorin 4D, and IL-8." (PMID 29541408, 2018). "We believe the reduction in tumor size associated with early EGF treatment was due to EGFR-induced changes in the tumor microenvironment, including decreased cytokine expression, resulting in early epigenetic, mutational, or clonal reprogramming of tumor cells that retarded their overall growth." (PMID 29904166, 2018).
tumor (continued). "EGF concentration in tumors may also be increased by the paracrine mechanism, for example, through EGF production by tumor-associated macrophages." (PMID 29268862, 2017). "Growth factors secreted by perivascular tumor-associated macrophages, such as the epidermal growth factor (EGF), could also promote local survival and proliferation of tumors that take up residence near vessels." (PMID 23730620, 2013). "Downregulation of ERBB3 in NB might suggest similar kinase switching during the EMT followed by tumor survival with the loss of EGF dependency." (PMID 23135478, 2013). "As EGFR overexpression is associated with highly aggressive and metastatic tumor cells, EGF-SubA+PDT combination might be particularly effective against primary invasive tumors either alone or in an adjuvant setting to surgery." (PMID 23887632, 2013). "Interestingly, we observed EGF-induced alternative promoter usage of genes that have previously been implicated in tumor progression (e.g., VEGFC, PTK2, IL18 and VAV3) or in cell survival/proliferation (e.g., FBXW7, BID, ABL2)." (PMID 24324612, 2013). "Moreover, EGF-induced transcription was abolished by MUC1 knockdown, supporting a critical role for MUC1 in the EGF-dependent transcription of genes linked to tumor cell invasion." (PMID 22586492, 2012). "However, the molecular mechanisms underlying the effect of EGF/EGFR on tumor cell migration are not completely understood to date." (PMID 22701712, 2012). "In addition to stimulating tumour cell proliferation, EGF signalling has also been implicated in modulating functions of stromal cells in the tumour microenvironment, such as tumour-associated angiogenesis and bone metastasis." (PMID 20010942, 2010). "Oral administration of abalone visceral extract significantly lowered tumor progression and metastasis by down-regulating the tumor-associated growth factors such as Cox-2, EGF, VEGF and FGF, while increasing the proliferation and cytolytic activity of CD8+ T cells." (PMID 20961430, 2010). "EGF induced signaling has often been associated with tumor invasion and metastasis." (PMID 18549507, 2008). "Likewise, EGF overexpression has been associated with tumour invasion and progression." (PMID 38256245, 2024). "M1 macrophages could produce inflammatory cytokines such as interleukin (IL)‐6 and IL‐1β, killing tumour cells and pathogenic microorganisms whereas M2 macrophages secret growth factors such as epidermal growth factor (EGF) participating in the tissue remodelling or tumour progression." (PMID 38680032, 2024). "Furthermore, we found that the treatment of tumor promoters, such as EGF or bFGF, shows a higher level of chromatin association of cGAS compared to the cGAS-S120A/T130A mutant, while the eluted cGAS from chromatin by NaCl addition was vice versa compared to remaining pellet fraction." (PMID 39424777, 2024). "Also, individualizing organoid culture media to target driver mutations in the patient tumor genetic profile, such as EGF-depleted media to enrich for KRAS mutants, may increase PDO formation and eliminate nontumor “contaminants” that may inhibit PDO growth." (PMID 36256477, 2022). "Moreover, EGF may be combined with osteogenic scaffolds to fill large bone losses caused by traumas or tumours." (PMID 34955078, 2022). "EGFR and its ligands (e.g., EGF, transforming growth factor-alpha) are overexpressed in up to 90% of head and neck cancer patients, are further induced by standard of care external beam radiation and DNA damaging agents, and are strongly linked to tumor progression." (PMID 35569509, 2022). "Moreover, it is plausible that PD-L1–mediated activation of p38-MAPK could be synergistic with the activation of conventional tumor-promoting signals like EGF and can be further activated by PD-1 expressed in the tumor-associated microenvironment." (PMID 33884962, 2021).
tumor (continued). "However, bevacizumab reduces vascular density and causes hypoxia in the tumour, which may induce angiogenic factors, such as HB-EGF, BTC and EGF, which are also high-affinity EGFR ligands." (PMID 32605298, 2020). "EGF might be associated with tumour growth and invasion as a molecule downstream of K19." (PMID 27863477, 2016). "Tumor associated macrophages (TAMs) are enriched for cells with this M2 polarized phenotype, which have been suggested to promote tumor cell growth, invasion and metastasis by secreting paracrine-acting and extracellular matrix remodeling factors including EGF, MMP and VEGF." (PMID 27563494, 2015). "In addition, the presence of tumor associated macrophages in breast tumors also correlates with poor prognosis and, in mouse models, CSF-1 promotes metastasis, stimulates angiogenesis and is involved in a paracrine loop with EGF to promote tumor cell invasion." (PMID 22096574, 2011). "Meanwhile, the SSP forms an interactive network with tumor signaling pathways including Akt, mTOR, and EGF-ERK, collectively driving metabolic reprogramming." (PMID 41816347, 2026). "Conversely, in EGFR-dependent tumors, PTP1B suppresses tumor growth by dephosphorylating EGFR upon EGF stimulation." (PMID 41522352, 2026). "The pathways affected are: Ephrin Receptor Signaling, TGF-β Signaling, STAT3 Pathway, EGF Signaling, Tumor Microenvironment Pathway, BAG2 Signaling Pathway, H-17A Signaling Pathway, EIF2 Signaling." (PMID 41717271, 2026). "Although the exosomes modestly increase cell proliferation in vitro, the EGF-Exo-DOX formulation exhibits enhanced tumor accumulation relative to the heart, minimal cardiac uptake, and shows no tumorigenic effects in vivo." (PMID 41593600, 2026). "The EGF-Exo was effectively internalized by tumor cell lines in a manner dependent on EGFR expression levels, and exhibited enhanced accumulation in xenograft A549 tumors relative to the heart, with minimal cardiac accumulation." (PMID 41593600, 2026). "A well-known positive feedback loop is the Endothelial Growth Factor–Colony Stimulating Factor-1 (EGF-CSF-1) circuit: Tumor cells release CSF-1 to recruit and differentiate macrophages, while TAMs secrete EGF, which enhances tumor cell migration and invasion." (PMID 41597210, 2026). "PDOs are developed by culturing dissociated tumor tissues in an organoid medium enriched with EGF, bFGF, and ROCK inhibitor Y-27632." (PMID 40647519, 2025). "They secrete the Interleukins (IL-) IL-4, IL-6, IL-8, and IL-10, TGF-β (Transforming Growth Factor), EGF (Epidermal Growth Factor), and other factors that facilitate tumour growth and cell migration." (PMID 41009413, 2025). "PDCD4, a tumor suppressor that is downregulated in many cancers, is also suppressed by serum, EGF, or TPA treatment." (PMID 41439995, 2025). "Across all nodal stages (N0 to N3), promoter methylation levels of CCL18 and EGF remained significantly lower in tumor samples compared to normal tissue (normal: 97; N0 = 230; N1 = 242; N2 = 97; N3 = 20; p < 0.05)." (PMID 40692603, 2025). "The mutations predominantly occurred in the extracellular epidermal growth factor (EGF) domain (n = 87/112; 70/87 of these tumours were dMMR), with a hotspot at p.A465T identified (n = 10; COSM1217602)." (PMID 41419736, 2025). "EGF is a well-known growth factor that drives tumor cell proliferation and survival through its activation of the EGFR signaling pathway." (PMID 40584614, 2025). "Apoptotic cells can release mitogenic signals, such as EGF, stimulating proliferation in neighbouring cells and contributing to tumour repopulation." (PMID 40769969, 2025). "This study showed that in the presence of EGF in the tumor microenvironment, the HNMT and HER2 proteins can form a complex, leading to the shedding of the cytosolic HER2-ICD domain." (PMID 39789599, 2025).